CX3CL1 (C-X3-C motif chemokine ligand 1)
Diseases named in the same sentence as CX3CL1 in open-access papers (continued):
Sharing a sentence is not in itself a finding about the gene and the disease.
cancer (continued). "Deletion of Cx3cl1 in cancer cells decreased myeloid cell infiltration associated with Vhl loss to provide a mechanism by which Vhl loss may have contributed to the altered immune landscape." (PMID 38618956, 2024). "Additionally, the CNA and mutation frequency of CX3CL1 in pan-cancer were investigated, and it was discovered that CX3CL1 undergoes considerable gene alterations in various cancer types, with the highest proportion of missense mutation and amplification." (PMID 37153002, 2023). "CX3CL1 is more likely to be mutated in cancers in which it is significantly upregulated." (PMID 37153002, 2023). "As recorded by the UALCAN database, there are 15 cancer types linked to CX3CL1 methylation." (PMID 37153002, 2023). "In the co-cultures, G-CSF and GM-CSF could account for the viability and proliferation of macrophages, in addition to their own production of M-CSF, as well as fractalkine/CX3CL1, which has been implicated in anti-cancer responses." (PMID 34572807, 2021). "We then evaluated whether CX3CL1 expression is associated with cancer cell proliferation and invasiveness." (PMID 34671562, 2021). "CX3CL1 mRNA was identified as the direct downstream target of miR-561-5p, with miR-561-5p overexpression in HCC patients reducing CX3CL1 levels, indicating that the crosstalk between cancer cells and their associated stroma cells is potentially regulated by CX3CL1." (PMID 31367257, 2019). "In this study, we propose that CX3CL1 is associated with the process of spinal metastases derived from different primary cancers, which coincides with previous findings that CX3CL1 exhibits chemotaxis of different cancer cells." (PMID 28122354, 2017). "Increasing the expression of CX3CL1 in tumors has a therapeutic effect and can be used as one of the elements of immunotherapy and as an auxiliary means to improve the efficacy of anti-cancer treatment." (PMID 41169393, 2025). "CX3CR1 is expressed in various types of cancer cells, transmitting signals induced by CX3CL1 and participating in the proliferation and metastasis of malignant tumors." (PMID 38466034, 2024). "These outcomes were due to double-faced CX3CL1 effects on different immune microenvironments indolent and aggressive cancer created." (PMID 38775151, 2024). "To identify the influence of CX3CL1 on the characteristics of MOC cancer cells, we performed MTS and Transwell migration assays to evaluate cell proliferation and migration efficacy, respectively." (PMID 38775151, 2024). "In conclusion, CX3CL1 is a pivotal factor that stimulates the metastasis of aggressive cancer subclones within the heterogeneous tumors to metastasize, and our study demonstrates the prognostic value of CX3CL1 enrichment in long-term monitoring in OSCC." (PMID 38775151, 2024). "CX3CR1 is a high-affinity chemokine receptor of CX3CL1 that is expressed in immune cells such as T cells, NK cells, and macrophages, as well as in some cancer cells." (PMID 38775151, 2024). "CX3CL1 was the focus of our study because of its multifaceted roles in cancer and the limited number of studies on CX3CL1 in OSCC." (PMID 38775151, 2024). "This indicates the exclusivity of CX3CL1 release during immunogenic apoptosis, suggesting its potential role in mediating immunogenicity of cancer cells undergoing apoptotic ICD." (PMID 39011040, 2024). "Several studies have evidently shown that chemokines (such as CCL2, CCL5, CXCL1, and CX3CL1) are involved in neuronal sensitization or microglia activation in the spinal cord, and some of these chemokines contribute to the development of cancer pain." (PMID 39641645, 2024). "Our study reported that CX3CL1 functioned differently in tumors with different cancer phenotypes, both in vivo and in vitro." (PMID 38775151, 2024).
cancer (continued). "The results of these studies supported the significant role of NK cell activity in antitumor effects against CX3CL1-positive cancers." (PMID 39457710, 2024). "To assess the potential relevance of our findings in humans, we performed pan-cancer analyses of CX3CL1 and CX3CR1." (PMID 38618956, 2024). "Around the cancer nest regions, the CX3CL1 enrichment patient group exhibited an increased number of PDPN+ structures compared with CX3CL1-stable patients." (PMID 38775151, 2024). "CX3CL1 expression enrichment in metastasis models indicates that the cancer character changed to a more aggressive nature." (PMID 38775151, 2024). "In this study, we investigated the intricate role of CX3CL1 in immunogenic apoptosis induced by mitoxantrone (MTX) in cancer cells." (PMID 39011040, 2024). "The expression of CX3CL1 was higher in LUSC, STAD and LIHC, and lower in KICH, KIRC, and OV during tumors progression, indicating that CX3CL1 plays a critical role in the carcinogenesis and progression of these cancers." (PMID 37153002, 2023). "Approximately 32% of the cancer types with significantly differential expression were adenocarcinomas, suggesting a specific role for CX3CL1 in adenocarcinomas." (PMID 37153002, 2023). "CX3CL1 had significant differential expression in 19 out of 33 TCGA cancer types, including ACC, BLCA, BRCA, CHOL, DLBC, HNSC (HPV pos./neg)." (PMID 37153002, 2023). "CX3CL1 showed significant differential expression in approximately 58% of TCGA cancer types, according to the results." (PMID 37153002, 2023). "The increase in CX3CL1 chemokine levels can be attributed to the interaction of 4T1/GFP cancer cells with IL-4." (PMID 37445941, 2023). "The disparities in CX3CL1 expression were discovered when patients suffering from various types of cancer were segmented into two categories, based on their ages." (PMID 37153002, 2023). "It has been reported that CX3CL1 plays a crucial role in regulating cell adhesion, migration, and survival of human cancer cells." (PMID 37875556, 2023). "CX3CL1 plays a vital role in regulating cell adhesion, migration and survival of human cancer cells." (PMID 37082943, 2023). "On the other hand, CX3CL1 promotes cancer cells proliferation and migration, and contributes to angiogenesis, which were significantly inhibited by the administration of CX3CL1-neutralizing antibodies." (PMID 37153002, 2023). "The genome-wide pan-cancer analysis is advantageous for elucidating the correlation between the expression of CX3CL1 and carcinogenesis, which in turn informs the development of more effective surveillance, diagnosis, and treatment strategies." (PMID 37153002, 2023). "NF-kB mediates cancer development and progression, and we found that NF-kB mRNA was upregulated upon CX3CL1 addition indicating a relationship between CX3CR1 activation and NF-kB signaling." (PMID 37771579, 2023). "The CXCL2, CXCL12, and CX3CL1 genes of this signature were shown to be significantly expressed in monocytes and cancer cells, according to scRNA-seq analysis." (PMID 37021054, 2023). "In order to investigate the potential function of CX3CL1 in the clinical prognosis and immunotherapy, I evaluated the expression of CX3CL1 in numerous cancer types, methylation levels and genetic alterations." (PMID 37153002, 2023). "Further analysis revealed that there is a potential relationship between CX3CL1 expression and immune cells in the TME and that CX3CL1 can thus influence cancer immunotherapy." (PMID 36397015, 2022). "We aimed to analyze cancer immunity regulation by CX3CL1; therefore, we explored the correlation between CX3CL1 expression and immune cell infiltration into the TME." (PMID 36397015, 2022). "This expansion was associated with a significant increase in CX3CL1 and a reduction in CCL2 levels in cancer patients’ sera." (PMID 35053248, 2022).
cancer (continued). "TCGA and GTEx data from the UCSC Xena database were employed to evaluate the expression levels of CX3CL1 in cancer tissues compared with those in normal tissues." (PMID 36397015, 2022). "In general, these data confirm the potential ability of CX3CL1 in predicting the response to immunotherapy and show that CX3CL1 is a promising biomarker for cancer immunotherapy." (PMID 36397015, 2022). "Recently some research found one such chemokine that plays a critical role in the anti-cancer procession is CX3C chemokine ligand 1 (CX3CL1) and its receptor CX3C chemokine receptor 1 (CX3CR1)." (PMID 35734169, 2022). "Especially the high expression of genes encoding CX3CL1, CXCL9 and CXCL10 has been found in carcinomas highly infiltrated by effector TCs, particularly TH1, which show higher overall and disease-free survival." (PMID 35954497, 2022). "Mo-MDSC recruitment by the two chemokines takes place mainly during hypoxia, when the expression of eotaxin-3/CCL26 and CX3CL1 increases in cancer cells." (PMID 32466280, 2020). "Next, we present the role of CX3CL1 in the context of cancer, with the focus on angiogenesis, apoptosis resistance and migration and invasion of cancer cells." (PMID 32466280, 2020). "While CCL2, CXCL10, and CX3CL1/CX3CR1 can serve as favorable or unfavorable prognostic factors depending on the cancer types, CCL14 and XCL1 possess good prognostic value." (PMID 31991604, 2020). "One such chemokine that plays an important role in the cancer process is CX3C chemokine ligand 1 (CX3CL1) along with its receptor CX3C chemokine receptor 1 (CX3CR1)." (PMID 32466280, 2020). "Autophagy-related genes BID, EIF4EBP1, VMP1, SPHK1, and CX3CL1 also play essential roles in other cancers." (PMID 33224313, 2020). "Since the discovery of CX3CL1 more than 20 years ago, a number of studies on its role in cancer processes have been undertaken." (PMID 32466280, 2020). "Most of the genes in the subnetworks were inflammatory cytokines and participated in TNF signaling pathways and pathways in cancer, such as Ccl2, Ccl20, Csf1, Cx3cl1, Cxcl1, Cxcl3, Il6, Birc3, Map3k8, Nos2, Nfkb2, Tnfrsf1b, and Vcam1." (PMID 33042984, 2020). "This anti-inflammatory cytokine, playing an important role in the development of cancer, reduces the expression of CX3CL1 in cancer cells and cancels the action of pro-inflammatory cytokines on CX3CL1 expression in vessel walls." (PMID 32466280, 2020). "The production of CX3CL1 by cancer cells enables TAM migration to the vicinity of these cells, followed by the cross-talk of TAM and cancer cells through intercellular signaling." (PMID 32466280, 2020). "This expansion was associated with a significant increase in CX3CL1 and reduction of CCL2 in cancer patients' sera." (PMID 30930117, 2019). "In both cancer and inflammation processes, CX3CL1 has been shown to stimulate chemotaxis, recruiting cells that expressed CX3CR1, such as natural killer (NK) cells, dendritic cells (DCs), and monocytes." (PMID 30845779, 2019). "Previous studies have indicated that fractalkine/CX3CL1 expression is related with the progression of many cancers." (PMID 28903329, 2017). "We therefore suggest that CX3CL1 represents a novel molecular target for cancer therapy, especially in combination with CDK inhibitors." (PMID 29234059, 2017). "By analogy with its role in the leukocyte adhesion, CX3CL1 obviates the need for both the association with proteoglycans and other adhesion molecules to bind CX3CR1-expressing cancer cells rapidly and with high affinity." (PMID 28122354, 2017). "CX3CL1 was expressed only by the normal and cancer adjacent normal fallopian tube epithelium; its expression was largely lost in the inflammatory and malignant fallopian epithelium." (PMID 26633537, 2015).
cancer (continued). "In conclusion, two different mechanisms operate in cancer, leading to protumoral or antitumoral effects of CX3CL1." (PMID 24799766, 2014). "In this view, CX3CL1−/− transgenic mice inoculated with cancer cells show a strong reduction of skeletal dissemination compared to wild-type animals." (PMID 24799766, 2014). "Epithelial cells from the surface of the ovary and the Fallopian tubes and from benign, borderline and malignant tumors all stained positive for CX3CL1." (PMID 21750716, 2011). "We then found that GILZ increased the production of CX3CL1 transcripts and proteins, consistent with a transcriptional regulation of CX3CL1 by GILZ in malignant tumor cells." (PMID 21750716, 2011). "GILZ overexpression in the carcinoma-derived BG1 cell line resulted in parallel changes in CX3CL1 products." (PMID 21750716, 2011). "In addition, studies have shown that CX3CL1 plays a crucial role in regulating the cell adhesion, migration, and survival of human cancer cells." (PMID 41445742, 2025). "The CX3CL1-CX3CR1 signaling axis, formed by a ligand–receptor interaction between transmembrane CX3CL1 and its cognate receptor, modulates malignant phenotypes encompassing proliferation, migration, invasion, and apoptosis resistance in cancer, suggesting its therapeutic relevance." (PMID 41267985, 2025). "CX3CL1 (or fractalkine) is a chemokine that has recently gained relevance in cancer." (PMID 41210693, 2025). "Similarly, CX3CL1 produced by osteoblasts and endothelial cells aids in the retention of cancer cells via CX3CR1 receptors." (PMID 40606222, 2025). "This highlights the complex and context-dependent nature of CX3CL1’s function in cancer biology." (PMID 41445742, 2025). "CXCL17 and CX3CL1 were positively correlated with SUSD4 expression level in most types of cancer." (PMID 38579174, 2024). "Alternatively, cancer cells release ‘find me’ signals that recruit monocyte or macrophage recruitment toward apoptotic cells, including lipid lysophosphatidylcholine, sphingosine 1-phosphate, fractalkine CX3CL1, and nucleotides ATP and UTP." (PMID 39092762, 2024). "In contrast, CX3CL1/CX3CR1 signaling has been associated with neurotropic metastasis in pancreatic ductal adenocarcinoma, increased cancer cell proliferation in ovarian cancer, and enhanced invasion and migration in lung cancer through activation of Src/FAK pathways." (PMID 39409924, 2024). "The highly aggressive cancer, MOC2, exhibits higher CX3CL1 expression than the indolent cancer." (PMID 38775151, 2024). "Interestingly, CX3CL1 overexpression produced similar results between indolent and aggressive cancer cells in the in vitro experiments." (PMID 38775151, 2024). "The addition of CX3CL1 to other treatments could affect their immunogenicity, unleashing their full immunogenic potential during cell death in anti-cancer therapy." (PMID 39011040, 2024). "However, in vivo, CX3CL1 increased keratinization in indolent MOC1 cancer, while CX3CL1 promoted cervical lymphatic metastasis in aggressive MOC2 cancer." (PMID 38775151, 2024). "To investigate whether CX3CL1 overexpression in cancer cells can attract the CX3CR1+ cells into the TME, we stained and counted the CX3CR1+ cells in the TME of MOC1 and MOC2 tumors." (PMID 38775151, 2024). "Doses of 1 ng, 10 ng or 100 ng of murine rCX3CL1 were added to the non-immunogenic dose of MTX-treated cancer cells to analyse whether the addition of CX3CL1 can enhance the immunogenicity of dying cancer cells." (PMID 39011040, 2024). "This will help paint a clearer picture of the roles CX3CL1 plays in human cancers." (PMID 37153002, 2023). "Additionally, it was also proven that blocking CXCL10 enhanced morphine antinociception in cancer-induced bone pain and, from another chemokine family, CX3CL1 plays an important role in regulating morphine analgesia in naive animals." (PMID 37190544, 2023). "Therefore, the cBioPortal database was used to conduct the investigation of CX3CL1’s genetic changes in various cancer types." (PMID 37153002, 2023).
cancer (continued). "The CX3CR1 is a specific receptor for CX3CL1 and is involved in CX3CL1‐mediated cancer progress." (PMID 37082943, 2023). "Nerve-derived C-X3-C motif chemokine ligand 1 (CX3CL1) and NT-3 further support the interaction between nerve tumors, and the former enhances the adhesion between cancer cells and nerves, while the latter regulates the interaction between SCs and cancer cells." (PMID 36900158, 2023). "The signature genes CXCL2, CXCL12 and CX3CL1 were mainly expressed in cancer cells and monocytes." (PMID 37021054, 2023). "Last, CX3CL1/CX3CR1 play a role in bone metastasis of other cancers, including breast cancer." (PMID 37025604, 2023). "Evidence for the first hypothesis can be drawn from the cancer field, in which anti-cancer properties have been attributed to CX3CL1." (PMID 38250083, 2023). "Furthermore, CX3CL1 was variably expressed in methylation levels and gene alterations in most cancers according to The Cancer Genome Atlas (TCGA)." (PMID 37153002, 2023). "Therefore, the correlation between CX3CL1 and ICAM‐1 or VCAM‐1 is explored in the present study, showing that only CX3CL1‐induced ICAM‐1 expression is observed, indicating that ICAM‐1 plays a vital role in CX3CL1‐induced cancer metastasis." (PMID 37082943, 2023). "To date, research on CX3CL1 in cancer has been limited to a single type of cancer." (PMID 37153002, 2023). "Except for BAI1, CD31, and MerTK, the enhanced expression of Axl, Tyro3, Gas6, MFGE8, Stab2, Tim-4, CX3CL1, IDO1, Rac1, and PD-L1 was associated with decreased sensitivity to many drugs, which may partially explain the resistance to chemotherapy in cancers." (PMID 36059952, 2022). "CX3CL1 is expressed in breast, pancreatic, gastric and colon cancers." (PMID 35211124, 2022). "The pan-cancer expression pattern and prognostic value of CX3CL1 were evaluated in this study." (PMID 36397015, 2022). "In this study, we investigated the anti-cancer effects of CX3CL1 in ccRCC." (PMID 35734169, 2022). "CX3CL1 is considered an essential chemokine in regulating cancer progression." (PMID 36397015, 2022). "Therefore, we believe that one of the mechanisms through which CX3CL1 affects patient prognosis in cancers is by influencing the host immune response." (PMID 36397015, 2022). "The importance of CX3CL1 in cancer biology is still being discussed and remains controversial." (PMID 34070094, 2021). "Trastuzumab treatment showed pronounced efficiency in CX3CL1 overexpressing cancer cells compared to low expressing cells preventing lung metastasis, while the administration of CX3CL1 shedding inhibition did not cause an enhanced treatment effect." (PMID 34070094, 2021). "This study suggests that CX3CL1 might promote the cancer progression through the ERK/MAPK signaling pathway." (PMID 34671562, 2021). "Additionally, the crucial role of CX3CL1 was shown within the process of trans-endothelial migration of cancer cells." (PMID 34063821, 2021). "It is even postulated using gene therapy in transferring CX3CL1 to cancer cells." (PMID 32466280, 2020). "It seems that this CX3CL1-dependent recruitment occurs only in some cancers." (PMID 32466280, 2020). "CX3CL1 also participates in the recruitment of cells to a cancer niche." (PMID 32466280, 2020). "Therefore, some chemokines such as CCL2, CXCL10, and CX3CL1/CX3CR1 can be either favorable or unfavorable cancer prognostic factors depending on the cancer types." (PMID 31991604, 2020). "This work focuses on the ‘hallmarks of cancer’ involving CX3CL1 and its receptor CX3CR1." (PMID 32466280, 2020). "The CXC3R1/CX3CL1 interaction is essential for the metastasis of cancer cells." (PMID 31077234, 2019). "Based on these studies and our observation, it is plausible to hypothesize that the endothelial cells lining the bone marrow sinusoids express membrane-associated CX3CL1, which can provide viable docking sites for circulating CX3CR1-expressing cancer cells." (PMID 28122354, 2017).